KLF15 (KLF transcription factor 15)
Diseases named in the same sentence as KLF15 in open-access papers (continued):
Sharing a sentence is not in itself a finding about the gene and the disease.
gastric cancer (8 papers, 2020 to 2025). A primary or metastatic malignant neoplasm involving the stomach. "For example, KLF15 positively mediated lncRNA TFAP2A-AS1 to suppress gastric cancer cell proliferation and migration." (PMID 38273088, 2024). "KLF15 has been reported to inhibit cell growth in lung adenocarcinoma, gastric cancer, and colorectal cancer, and can be used to predict prognosis." (PMID 33042807, 2020). "KLF15 was shown to be downregulated in gastric cancer but increased in lung cancer." (PMID 35345512, 2022). "In addition, low KLF15 expression level indicates a poor prognosis of gastric cancer patients." (PMID 37936130, 2023). "In cellular experimental studies of a gastric cancer model, overexpression of KLF15 promotes apoptosis and autophagy through PI3K/Akt/ mTOR promoted apoptosis and autophagy, and inhibited the proliferation and invasion of gastric cancer cells." (PMID 40429972, 2025). "We focused on KLF6 and KLF15 as the interaction between miR-181a-5p and KLF6 has been previously demonstrated in gastric cancer, and KLF6 and KLF15 were putative tumor suppressors in BC." (PMID 32998707, 2020).
Hepatic steatosis (7 papers, 2013 to 2025). Steatosis is a term used to denote lipid accumulation within hepatocytes. "Under high-fat feeding conditions, protection against hepatic steatosis in KLF15-/- mice is associated with increased hepatic ER stress, suggesting that KLF15 may be required for ER stress-induced hepatic lipid accumulation." (PMID 24167585, 2013). "Peroxisome proliferator-activated receptor α (PPARα) or Kruppel-like factor 15 (KLF15) can also ameliorate hepatic steatosis through inhibition of SREBP-1c activation to reduce the synthesis of fatty acids and triacylglycerols." (PMID 39911797, 2025). "In KLF15−/− mice, enhanced fatty acid oxidation inhibited the mTORC1 signaling pathway, thereby improving hepatic steatosis." (PMID 36937859, 2023). "Protection against both HFD and ER stress-induced hepatic steatosis is likely to contribute to increased hepatic insulin sensitivity in KLF15-/- mice." (PMID 24167585, 2013). "Thus, KLF15-/- mice are protected against HFD-induced hepatic steatosis." (PMID 24167585, 2013). "Thus, compared to WT controls, KLF15-/- mice are protected against ER stress-induced fatty liver." (PMID 24167585, 2013). "For instance, five variants in or near TM6SF2, PNPLA3, HFE, APOE, and MTARC1 had comparably larger effects on HCC than on hepatic steatosis (p <0.05 by Cochran’s Q test), while HCC-associated variants in HSD17B13, KLF15, and TERT did not significantly associate with steatosis." (PMID 40823170, 2025).
Hypoglycemia (7 papers, 2013 to 2023). A decreased concentration of glucose in the blood. "Recent studies have shown that mice with KLF15-targeted deletion (KLF15−/−) caused severe hypoglycemia after overnight (18 h) fasting compared with control animals." (PMID 36937859, 2023). "In support of these observations, mice with targeted global deletion of KLF15 developed fasting-induced hypoglycemia due to impaired amino acid degradation and reduced availability of metabolites for glucose production." (PMID 36902112, 2023). "Evidence suggested that defects in amino acid catabolism, leading to fasting hypoglycemia at KLF15−/− mice through limiting the availability of gluconogenic substrates." (PMID 36937859, 2023). "KLF15 knockout mice display severe hypoglycemia after fasting due to defective amino acid catabolism." (PMID 24358263, 2013). "Our study began with the unexpected observation that Klf15−/− mice, despite having chronic hypoglycemia and substantially elevated plasma glucagon concentration, had inappropriately low plasma concentration of total corticosterone, the predominant circulating corticosteroid hormone in mice." (PMID 35263131, 2022). "Likewise, KLF15 deletion in mice produces hypoglycemia and impaired amino acid catabolism upon fasting." (PMID 29180716, 2017). "Indeed, KLF15-/- mice exhibit decreased plasma glucose levels in the fed state and hypoglycemia after an overnight fast." (PMID 24167585, 2013). "Consequently, supplementation of pyruvate to Klf15−/− mice attenuated fasting hypoglycemia." (PMID 36902112, 2023).
colorectal cancer (6 papers, 2020 to 2024). A primary or metastatic malignant neoplasm that affects the colon or rectum. "Here, we show that KLF15, a transcription factor, exhibits the reduced expression in colorectal cancer." (PMID 38273088, 2024). "The lncRNA TTN-AS1 upregulates Kruppel-like factor 15 (KLF15) expression to accelerate colorectal cancer development by sponging miR-376a-3p." (PMID 34903127, 2021). "For instance, lncRNA TTN-AS1 sponged miR-376a-3p to promote colorectal cancer progression via upregulating KLF15." (PMID 34090483, 2021). "KLF15 is highly expressed in colorectal cancer tissue and promotes tumor growth." (PMID 37853052, 2023). "Our findings highlight a regulatory network involving KLF15, LINC00689, PTBP1, LATS2, and the YAP1/β-catenin pathway in colorectal cancer, shedding light on potential therapeutic targets for colorectal cancer therapy." (PMID 38273088, 2024).
endometriosis (6 papers, 2015 to 2024). The growth of functional endometrial tissue in anatomic sites outside the uterine body. "This may indicate a potential role of KLF15 in the development of endometrial receptivity and could contribute to the embryo implantation failure seen in women with endometriosis-associated infertility." (PMID 38513352, 2024). "Our research has revealed crucial insights into the involvement of KLF15 in endometriosis-related infertility." (PMID 38513352, 2024). "They revealed that the progesterone receptor directly binds to KLF15, a transcription factor in mid-secretory epithelial endometrial cells, leading to reduced KLF15 expression in endometriosis patients due to progesterone resistance." (PMID 39338174, 2024). "In our research, we found that there is a decrease in both KLF15 protein and mRNA expression in the eutopic endometrium of women with endometriosis, particularly during the mid-secretory phase." (PMID 38513352, 2024). "To further investigate this, we examined the protein expression of KLF15 in the endometrium of infertile women with endometriosis using immunohistochemistry." (PMID 38513352, 2024). "The results of the GSE: 6364 datasets showed that KLF15 mRNA expression decreased in the eutopic mid-secretory endometrium of women with endometriosis." (PMID 38513352, 2024). "The expression of KLF15 was very weak in eutopic endometrium from women with endometriosis, while its expression was strong in endometrial cells in control endometrium." (PMID 26378916, 2015). "In addition to the protein expression, the expression of KLF15 mRNA was also found to be decreased in women with endometriosis compared to the control group during the mid-secretory phase, as detected by RT-qPCR analysis." (PMID 38513352, 2024). "However, in the mid-secretory phase of epithelial cells in the eutopic endometrium from women with endometriosis, the H-score of KLF15 was significantly lower." (PMID 38513352, 2024). "Finally, KLF13-null lesions contribute to defective steroid hormone receptor signaling in the pathology of endometriosis, and KLF15 negatively regulates E2-induced epithelial cell proliferation, which is associated with endometriosis and endometrial cancer." (PMID 26223982, 2015). "Particularly, a notable reduction in KLF15 expression was observed in the mid‐secretory epithelial endometrial cells of patients with endometriosis compared with individuals without the condition." (PMID 39263604, 2024). "Furthermore, multiple studies have discovered that KLF9, KLF11, KLF12, KLF15, and KLF16 are all involved in the occurrence and development of endometriosis." (PMID 39263604, 2024).
Hypertension (6 papers, 2012 to 2024). The presence of chronic increased pressure in the systemic arterial system. "Therefore, therapeutic targeting of the KLF15 or CXCL1/CXCR2 axis may serve as an innovative approach for the treatment of hypertension-associated cardiovascular disease." (PMID 33869197, 2021). "The association of KLF15 SNP genotypes with echocardiographic cardiac parameters were examined further using multiple linear regression analysis after adjusting for known risk factors for increased LV mass (age, gender, body mass index (BMI) and hypertension) in the dominant genetic model." (PMID 28400202, 2017). "The KLF15 SNP rs9838915 A allele was associated in a dominant manner with LV mass before (P = 0.003) and after (P = 0.001) adjustment for age, gender, body mass index (BMI) and hypertension, and with adjusted septal (P < 0.0001) and posterior (P = 0.004) wall thickness." (PMID 28400202, 2017). "SIRT7 overexpression mitigates this hypertension-related structural and functional damage in kidney cells by hyperactivating the Kruppel-like factor 15 (KLF15)/NRF2 axis in an angiotensin II (ANG II) infusion-induced hypertensive mouse model." (PMID 37676263, 2024). "Blockade of CXCL1/CXCR2 signaling attenuated KLF15 deficiency-induced accelerated cardiac remodeling, which provides a new KLF15/CXCL1 axis in regulation of hypertension-associated cardiac remodeling." (PMID 33869197, 2021). "However, little is known about the function of KLF15 in cardiac fibroblasts, which regulates inflammation response-mediated cardiac remodeling in hypertension." (PMID 33869197, 2021). "However, it’s important to identify the mechanism of the KLF15-mediated inflammatory response and its effects on cardiac cellular crosstalk in hypertension-induced cardiac remodeling." (PMID 33869197, 2021). "Recently, we found that KLF15 negatively regulates chemokine CCL2 expression, which recruits macrophages into injured arteries in hypertension." (PMID 33869197, 2021). "In conclusion, our study identifies that KLF15 in cardiac fibroblasts negatively regulates CXCL1/CXCR2 axis-mediated inflammatory response and subsequent cardiac remodeling in hypertension." (PMID 33869197, 2021).
lung adenocarcinoma (6 papers, 2017 to 2021). A carcinoma that arises from the lung and is characterized by the presence of malignant glandular epithelial cells. "In addition, KLF15 could propel lung adenocarcinoma cell proliferation and metastasis." (PMID 34727954, 2021).
type 2 diabetes (6 papers, 2017 to 2025). "We recently explored the genetic association of KLF15 single nucleotide polymorphisms (SNP) in patients with type 2 diabetes and an echocardiographic assessment of LV mass." (PMID 29702551, 2018). "The intronic KLF15 SNP rs9838915 A allele was significantly associated with LV mass and the association was replicated in an independent cohort of >5000 type 2 diabetes patients." (PMID 29702551, 2018). "Our finding in the discovery cohort that the rs9838915 SNP A allele in the KLF15 gene was associated with increased LV mass in type 2 diabetes was replicated in a large, independent cohort." (PMID 28400202, 2017). "We have identified the KLF15 SNP rs9838915 A allele as a marker of LVH in patients with type 2 diabetes, and replicated these findings in a large independent cohort." (PMID 28400202, 2017). "We conducted a clinical study investigating the association of KLF15 with echocardiographically determined LV mass in patients at high risk of LVH due to type 2 diabetes." (PMID 28400202, 2017). "A key finding in the discovery cohort was that the A allele at rs9838915 SNP in the KLF15 gene was associated with increased LV mass in patients with type 2 diabetes." (PMID 28400202, 2017). "Therefore, the findings of this study propose the KLF15 SNV rs9838915 A allele as a marker of left ventricle hypertrophy in patients with type 2 diabetes." (PMID 36836777, 2023). "The significance of KLF15 in human disease was illustrated by our recent paper which identified a variant in the KLF15 gene relevant to the development of LVH in patients with type 2 diabetes." (PMID 29970016, 2018). "This study investigated if KLF15 gene variants were associated with LVH in type 2 diabetes." (PMID 28400202, 2017). "We identified a gene variant, the rs9838915 SNP in the KLF15 gene that is relevant to increased LV mass in 318 patients with type 2 diabetes, and validated these findings in a large independent cohort of > 5000 individuals with type 2 diabetes." (PMID 28400202, 2017). "In conclusion, the four identified residues are essential to recognise KLF15 ZnF DNA binding and can be considered potential hotspots for the therapeutics development for type 2 diabetes." (PMID 40411314, 2025). "Genetic variations of KLF-15, documented as a hypertrophy inhibitor, have been studied in patients with type 2 diabetes." (PMID 36836777, 2023). "Our study provides evidence that genetic variation in KLF15 is associated with LVH in patients with type 2 diabetes and these findings were then replicated in an independent cohort of patients with type 2 diabetes." (PMID 28400202, 2017). "This clinical study investigated the association between the KLF15 gene and LVH in patients with type 2 diabetes." (PMID 28400202, 2017). "KLF15 negatively regulates cardiac fibrosis through SDF-1β in type 2 diabetes." (PMID 38516000, 2024). "Furthermore, we replicated the association of the KLF15 SNP rs9838915 A allele with LVH in a large, independent cohort of patients with type 2 diabetes, the Go-DARTS cohort (n = 5631)." (PMID 28400202, 2017).
cardiomyopathy (5 papers, 2020 to 2024). A disease of the heart muscle or myocardium proper. "Klf15 deficiency occurs in human cardiomyopathy and aortic aneurysms, and its deletion leads to cardiomyopathy and aortopathy in mice." (PMID 36949106, 2023). "Inhibition of p300 activity using curcumin rescued the pathological phenotype in Klf15-deficient mice, indicating the significance of p300 in Klf15 deficiency-induced cardiomyopathy and aortapathy." (PMID 32765954, 2020). "The epigenetic regulator p300 also plays a significant role in Klf15 deficiency-induced cardiomyopathy and aortopathy." (PMID 32765954, 2020). "Interestingly, acetyltransferase p300 is involved in Klf15 deficiency-induced cardiomyopathy and aortapathy as evidenced by the observation that acetyltransferase p300 inhibitor curcumin significantly ameliorates AngII-induced aortapathy and cardiomyopathy-related pathologies in Klf15 knockout mice." (PMID 34831061, 2021). "In functional assays using a dual-luciferase assay system, mutant KLF15 showed neither transcriptional activation of the KChIP2 promoter nor transcriptional inhibition of the CTGF promoter, alone or in the presence of TGFB1, a key player in the pathogenesis of arrhythmias and cardiomyopathies." (PMID 33809104, 2021).
asthma (4 papers, 2014 to 2025). "TNFα/IFNγ was found to augment the expression of several genes that contribute to airway inflammation, hypercontractility and remodeling in asthma while also reducing expression of key anti-inflammatory genes, such as KLF15." (PMID 35578269, 2022). "Many of them have been associated with asthma regulation, mainly SP3 and KLF15." (PMID 41154593, 2025).
atherosclerosis (4 papers, 2018 to 2025). A disease characterized by the build-up of fatty material and calcium deposition in the arterial wall resulting in partial or complete occlusion of the arterial lumen. "Smooth muscle–specific deficiency of KLF15 augmentes inflammatory signaling and accelerates atherogenesis in atherosclerosis." (PMID 38582447, 2024). "The functions of KLF15 in VSMCs have also been indentified in pathological states, such as atherosclerosis and postinjury neointima formation." (PMID 38582447, 2024). "Furthermore, several lines of evidence implicate the role of KLF15 in maintaining VSMCs function during the pathological conditions, including atherosclerosis and postinjury neointima formation." (PMID 38582447, 2024). "Besides, KLF15 was demonstrated to have a protective effect on atherosclerosis via inhibition of NF-κB signaling." (PMID 33869197, 2021). "Additionally, elevated expression level of IGFBP4 was detected in the atherosclerotic plaque and blood samples from people with atherosclerosis, suggesting a unique regulatory role for IGFBP4 in the plaque dynamics through KLF15/IGFBP4 axis." (PMID 40806552, 2025). "The distinct behavior of clade IV, which included two of the three liver specimens treated with carbon tetrachloride, did present distinctive enrichment of LXR/RXR activation and atherosclerosis signaling pathways, along with inferred activation of PPARA and KLF15." (PMID 29868123, 2018).
chronic kidney disease (4 papers, 2016 to 2021). Impairment of the renal function secondary to chronic kidney damage persisting for three or more months. "In this review, we discuss recent advances and update our overview of the functions of KLF15 in kidney biology, hoping to provide new perspectives on the progression and therapy of Chronic Kidney Disease (CKD)." (PMID 31523196, 2019). "KLF15 transcription factor as a direct GR target gene exhibits an extensive role in pathophysiologic progression of diverse disease in varied organs, such as heart fibrosis, cardiac lipid metabolism, hepatic gluconeogenesis, chronic kidney disease, muscle wasting, and airway hyperresponsiveness." (PMID 27051474, 2016).
Duchenne muscular dystrophy (4 papers, 2018 to 2024). Duchenne muscular dystrophy (DMD) is a neuromuscular disease characterized by rapidly progressive muscle weakness and wasting due to degeneration of skeletal, smooth and cardiac muscle. "Klf15 deletion exacerbates the dystrophic phenotype in mdx mice, a model of Duchenne muscular dystrophy, while 5-fold overexpression of Klf15 ameliorates the phenotype." (PMID 29942807, 2018). "Seeing as KLF15 is also aberrantly regulated in the muscle disease Duchenne muscular dystrophy (DMD), this transcription factor could act as a key integrator and/or biomarker of the metabolic and pathological state of muscle." (PMID 29735415, 2018).
Myocardial fibrosis (4 papers, 2021 to 2024). "Furthermore, myocardial fibrosis, α-SMA-positive myofibroblasts, and the mRNA expression of collagen 1a1 in KLF15 KO mice hearts were blunted by SB265610 treatment." (PMID 33869197, 2021). "Interestingly, there is convincing evidence demonstrating that KLF15 negatively regulates the expressions of CTGF and TGFB1, two key mediators of myocardial fibrosis, and can ameliorate or even reverse cardiac fibrosis and improve heart function." (PMID 33809104, 2021).
aortic stenosis (3 papers, 2017 to 2018). Aortic valve stenosis is a aortic valve disease caused by the incomplete opening of the aortic valve. "Aortic stenosis is a common cause of LVH and KLF15 expression has been examined in two experimental models of aortic constriction—transaortic constriction and aortic banding." (PMID 29702551, 2018). "In patients with LVH secondary to aortic stenosis, KLF15 protein was reduced in myocardial needle biopsy samples taken from the anterior LV of patients undergoing open heart surgery (n = 8) compared to patients undergoing coronary bypass grafting (n = 6)." (PMID 29702551, 2018). "There is also evidence that loss of cardiac KLF15 expression may contribute to pathological LVH in man with downregulation of ventricular KLF15 expression in patients with LVH secondary to aortic stenosis." (PMID 28400202, 2017). "Patients with LVH secondary to aortic stenosis compared to those without LVH, have significantly reduced KLF15 protein expression in the nuclei of myocytes." (PMID 29970016, 2018).